MMP2 (matrix metallopeptidase 2)
Diseases named in the same sentence as MMP2 in open-access papers (continued):
Sharing a sentence is not in itself a finding about the gene and the disease.
ovarian carcinoma (continued). "MMP2 and MMP9 have been previously reported to be direct target genes of miR-490-3p in ovarian cancer." (PMID 26714817, 2015). "However, previous studies have indicated that cellular interaction with Col I is mediated largely through integrin α1β1, α2β1 and α3β1 receptors, and cross linking of integrin β1 could activate MMP-2 in ovarian carcinoma cells, suggesting direct involvement of integrin signaling in MMP-2 activation." (PMID 25317077, 2014). "Besides, MMP-2 may be also involved in the occurrence, infiltration and transfer of ovarian cancer, and one of the molecular markers for ovarian tumor progression and molecular targets in ovarian cancer." (PMID 25347277, 2014). "Id1 can enhance EPC angiogenesis in ovarian cancer, which is mainly mediated by the PI3K/Akt and NF-κB/MMP-2 signaling pathways." (PMID 23714001, 2013). "Treating ovarian cancer cell lines SKOV3, OVCAR5 and IGROV1 with a PI3K inhibitor, LY294002, there is a reduction in gondatropin-induced MMP-2 activity with little change in MMP-9 activity." (PMID 23591839, 2013). "Tissue inhibitor of matrix metalloproteinases (TIMP) are naturally occurring inhibitors of MMPs, except for TIMP1 and TIMP2, which help activate MMP-2 and MMP-9, thereby playing a role in migration and invasion in ovarian cancer." (PMID 23591839, 2013). "MMP-2 and MMP-9 degrade collagen IV, the major structural collagen of the basement membrane, and are suggested to be critical in the metastatic process of ovarian cancer." (PMID 23593315, 2013). "The role of PEA3 in regulating MMP-2 and MT1-MMP expression has been demonstrated previously and inhibition of PEA3 expression using siRNA reduced MT1-MMP level by 50% in ovarian cancer cells." (PMID 23967226, 2013). "In another study assessing MMP-2, MMP-9 and MT1-MMP in 77 patients with ovarian cancer, strong epithelial MT1-MMP and stromal MMP-9 and FIGO stage were independently associated with shorter survival." (PMID 22200690, 2012). "We set out to analyze the epithelial and stromal expression of MMP-2, MMP-7, MMP-9, MT1-MMP, TIMP-1 and TIMP-2 in advanced epithelial ovarian cancers and to assess their prognostic value." (PMID 22200690, 2012). "About 15 studies have been published on the prognostic value of MMP-2, MMP-7, MMP-9, MT1-MMP, TIMP-1 or TIMP-2 in ovarian cancers, but the results remain controversial." (PMID 22200690, 2012). "We therefore, used a translational approach to analyze the epithelial and stromal expressions of MMP-2, MMP-7, MMP-9, MT1-MMP, TIMP-1 and TIMP-2 in advanced epithelial ovarian cancers and to assess their prognostic value." (PMID 22200690, 2012). "It is well established that increased MMP-2 and MMP-9 expression in ovarian cancer correlates negatively with prognosis and survival." (PMID 22022379, 2011). "Galectin-3 can be a tool to distinguish the proactive and active forms of MMP-2 and -9 and galectin-4 as a marker of MOC in ovarian cancer." (PMID 23658855, 2010). "In this study, we showed that overexpression of Lewis (y) increased MMP-2 and MMP-9 expression to promote migration and invasion of ovarian cancer cells." (PMID 21151448, 2010). "In ovarian cancer, ANPEP enhances tumor motility, MMP-2/VEGF secretion, and metastasis." (PMID 41465326, 2025). "The association between RBP4 and tumor size suggests that RBP4 may promote tumor growth, as also described in ovarian cancer, where RBP4 enhances migration and proliferation by activating RhoA/Rock1 and ERK pathways and upregulating MMP2 and MMP9." (PMID 41007818, 2025). "Induces apoptosis in ovarian cancer cells through caspase- and ROS-dependent pathways; reduces recruitment of TAMs by inhibiting chemokines MCP-1 and RANTES; suppresses M2 polarization of TAMs and reduces cancer-promoting factors like MMP-2, MMP-9, and VEGF." (PMID 40330466, 2025).
ovarian carcinoma (continued). "At the same time, related studies have found that the HE4‐encoding gene WFDC2 can induce the expression of matrix metalloproteinase 2 (MMP2) by activating the AKT signaling pathway, promote epithelial–mesenchymal transition, and then promote the metastasis of ovarian cancer cells." (PMID 38742362, 2024). "It was also noticed that PGRN could increase capacity in terms of the invasiveness and metastasis of breast and ovarian cancer via the upregulation of MMP-9 and the activation of matrix metalloproteinase 2 (MMP-2)." (PMID 38247816, 2024). "Clinical data have shown that Mmp2 is upregulated and positively correlated with the expression of the long lncRNA P73 antisense RNA 1T (TP73-AS1) in ovarian cancer tissues, and knockdown of Mmp2 attenuates the effects of TP73-AS1 overexpression on cell invasion and migration." (PMID 39769454, 2024). "In addition, the SMM extract significantly inhibited cell invasion and the expression levels of matrix metalloproteinase (MMP)-2 and MMP-9 in ovarian cancer cells." (PMID 37507925, 2023). "Notably, MMPs (such as MMP-2 (gelatinase A) and MMP-9 (gelatinase B)) have been introduced to degrade type IV collagen to facilitate cancer cell invasion and metastasis in ovarian cancer." (PMID 36658640, 2023). "Interestingly, in ovarian cancer, UGDH KD has been shown to negatively regulate levels of activated (phosphorylated) ERK with direct impacts on expression of MMP-2, MMP-9 and EMT-related factors further downstream." (PMID 37769033, 2023). "Similar to the mesenchymal subtype from the original TCGA study of ovarian cancer, S‐ECM shows upregulation of genes such as COL5A2, COL1A1, COL3A1, THBS2, COL11A1, COL6A3, and MMP2 that are involved in epithelial‐to‐mesenchymal transformation (EMT) processes, metastasis, and chemoresistance." (PMID 36637997, 2023). "In particular, MMP-2 and MMP-9 play critical roles in the metastasis of human ovarian cancer cells." (PMID 37507925, 2023). "MMP2 and MMP9 play important roles in the migration and invasion of ovarian cancer cells." (PMID 35621926, 2022). "In addition, we will construct an ovarian cancer xenograft tumor model and introduce STAT5A or JAK2 recombinant protein to verify the inhibition of MMP2 by high expression of STAT5A, thus affecting the invasion and migration ability of ovarian cancer." (PMID 36524006, 2022). "In addition, miR-199a-3p-Exo decreased the peritoneal dissemination in an ovarian cancer mouse model, and reduced the expression of c-Met, extracellular signal-regulated kinase (ERK) phosphorylation, and MMP2 in cancers." (PMID 35024437, 2022). "In addition, MMP2 and MMP16 transcripts, which are recognized proteins mediating enhanced migration and metastasis of ovarian carcinoma cells, were also reduced." (PMID 35562985, 2022). "It is speculated that MMP2 may act as a direct or indirect effect molecule of transcription factor STAT5A to promote the invasion and migration of ovarian cancer, which was in line with previous studies on esophageal cancer." (PMID 36524006, 2022). "Therefore, we investigated the effects of citromycin on MMP2 and MMP9 expression levels in human ovarian cancer cells." (PMID 35621926, 2022). "By contrast, some more recent research demonstrated that IL-8 promoted epithelial to mesenchymal transition (EMT) by increasing the MMP-2, MMP-9 and EpCAM expression, and stimulated the anchorage-independent growth, proliferation, angiogenic potential, adhesion and invasion in ovarian cancer cells." (PMID 35867729, 2022). "In addition, we showed that citromycin inhibited the invasion of ovarian cancer cells by downregulating the EMT marker gene expression levels and MMP2/9 activation via the ERK signaling pathway." (PMID 35621926, 2022). "Therefore, RAD21 likely promoted the progression of ovarian cancer by regulating the expression of MMP2 and MMP9, and its high expression predicted poor prognosis of ovarian cancer patients." (PMID 35860572, 2022).
ovarian carcinoma (continued). "For example, the migration and invasion ability could be increased by overexpressing TP72‐AS1 by positively regulating matrix metalloproteinase (MMP)‐2 and MMP9 in ovarian cancer cells." (PMID 34288373, 2021). "The expression of MMP-9, but not MMP-2, was associated with ERK activation and cancer invasion by CCL7 in human ovarian cancer cells." (PMID 34206004, 2021). "Moreover, SLT significantly inhibited the protein levels of MMP2, MMP9, and N-cadherin, and increased the protein level of E-cadherin, indicating that SLT can inhibit EMT in ovarian cancer cells." (PMID 33869638, 2021). "The results led to the conclusion that MMP-2 overexpression by cancer cells in peritoneal implants, but not in primary ovarian cancer, is predictive of ovarian cancer prognosis and more likely reflects the presence of highly aggressive clones of cancer cells." (PMID 32751899, 2020). "Moreover, they found that co-expression of MMP-2, MT1-MMP, and TIMP-2 within the same tumor seems to have an important role in ovarian cancer progression." (PMID 33287452, 2020). "Our results showed that miR-367 inhibited the expression of MCM2, MMP2, MMP9, and VEGF, suggesting that miR-367 may repress tumor cell proliferation, migration, invasion, and angiogenesis in ovarian cancer." (PMID 33024414, 2020). "Furthermore, overexpression of MMP‐2 and MMP‐9 was observed in ovarian cancer, and knockdown of both MMP proteins diminished the cell invasiveness of ovarian cancer." (PMID 32893977, 2020). "Furthermore, EGCC inhibited the metastasis of ovarian cancer cells by inhibiting the phosphorylation of c-Jun and NF-κB, resulting in the decreased expression of VEGF and the secretion of MMP-2 and MMP-9." (PMID 32934709, 2020). "Late passage was found to increase metastatic activity but not invasion through Matrigel®, and late passage of human ovarian carcinoma cells increased MMP-9 but not MMP-2 expression." (PMID 31489536, 2020). "Our data demonstrated that UGDH overexpressing TOV21GHI cells express higher levels of phosphorylated‐ERK, MMP‐2, SIP‐1 and SNAIL, whereas knockdown of UGDH leads to decreases in these markers, indicating that UGDH is involved in regulating ERK, MMP‐2 and EMT markers in ovarian cancer." (PMID 32893977, 2020). "However, a disaffinity was revealed in that when treating ovarian cancer cell lines with a PI3K inhibitor, LY294002, a reduction in gonadotropin-induced MMP-2 activity but with little change in MMP-9 activity was noted." (PMID 31295843, 2019). "Next, we assessed MMP-2 and MMP-9 activity in ovarian cancer cell lines." (PMID 29581841, 2018). "MMP2 was upregulated 3-fold and MMP-9 6.5-fold in ovarian cancer." (PMID 29581841, 2018). "Matrix metalloproteinases (MMPs), especially MMP-2 and MMP-9, are proteases that are capable of degrading the extracellular matrix to support cancer cell escape from the primary tumor site and metastasis in ovarian cancer." (PMID 29221185, 2017). "MMP-2 level is positively correlated with clinical stage and metastasis of ovarian cancer, but not with pathologic grading and age in ovarian cancer patients." (PMID 28538838, 2017). "In ovarian carcinoma cells, the VEGF/VEGFR loop promotes tumour invasion through induction of uPA and MMP-2, suggesting that blockade of the VEGF family might hinder tumour invasiveness." (PMID 28287096, 2017). "TCF21 inhibited MMP-2 and MMP-10 and decreased ovarian cancer cell invasion." (PMID 28476165, 2017). "MMP‐2 and MMP‐9 are upregulated in human ovarian carcinomas." (PMID 28401704, 2017). "We assessed the expression levels of MMP-2 and MMP-9 in mifepristone-treated ovarian cancer cells." (PMID 28938623, 2017). "In search for prognostic markers that could be useful in managing ovarian cancer, we focused on MMP-14 and MMP-2." (PMID 27038607, 2016). "We found that the expression of MMP9 but not MMP2 was markedly altered in both Rap1A overexpression and silencing ovarian cancer cells." (PMID 27925454, 2016).
ovarian carcinoma (continued). "In ovarian cancer, restored FSTL1 expression could inhibit tumor cell migration by reducing the secretion of matrix metalloproteinase 2 (MMP2)." (PMID 26918942, 2016). "Stress variables (MDA, AGEs, AOPPs, NO), profile of antioxidants (SOD, Catalase, Vitamin E & A, GSH, GRx, GPx) and inflammatory biomarkers (MMP-9, MMP-2, MMP-11, IL-1α and TNF-α) were biochemically assessed from venous blood of fifty ovarian cancer patients and twenty healthy control subjects." (PMID 27902750, 2016). "Although we could not fine the relationship between FN and MMPs expression in recent study, secreted FN enhances MMP-2 and MMP-9 expression through the MAPK and the PI3-K/Akt-dependent pathways in breast and ovarian cancer cells." (PMID 26637807, 2016). "MMP2 activity, as well as upregulation have been observed not only in brain tumours, but also in breast, colon, skin, lung, prostate and ovarian cancer." (PMID 26848686, 2016). "Whether through a decrease in MMP-2 or MMP-9 activity, inhibiting AKT phosphorylation results in a decrease in invasion, migration, and metastasis of ovarian cancer cells." (PMID 23591839, 2013). "Moreover, basigin-2 protein expression was significantly correlated with survival and the expression level of MMP-2/MMP-9 and malignant metastasis of ovarian cancer." (PMID 23566400, 2013). "It has been shown that treatment with adrenergic agonists could upregulate the production of matrix metalloproteinase (MMP)-2, MMP-9, and VEGF in ovarian cancer cell lines resulting in increased invasive capability." (PMID 23433478, 2013). "Interestingly, activation of NF-κB by Id1 led to the high expression of MMP-2, instead of VEGF, in EPCs from patients with ovarian cancer in the present study." (PMID 23714001, 2013). "Our correlation studies showed that expression of the TJ proteins claudin-6, occludin and MMP-2 were not correlated in ovarian cancer." (PMID 24245968, 2013). "We previously reported that desmoplastic stroma of ovarian cancers expressed MMP-2 and MMP-9, but not MMP-7." (PMID 24213462, 2012). "TGF-β produced by ovarian cancer cell line SKOVA3 activates omental fibroblasts, and direct interaction between the cancer cells and fibroblasts promotes invasion through increased expression of HGF and matrix metalloproteinase (MMP)-2." (PMID 24213462, 2012). "In addition to TGFβ, other central nodes (with both Ingenuity and MetaCore) include MMP2, p38MAPK, NFkB, and RAS, all known to be important in ovarian cancer." (PMID 19936259, 2009). "Trypsinogen, MMP-2, and MMP-9 are expressed in ovarian cancer." (PMID 11355948, 2001). "The results showed that MEnZn‐CuO NPs significantly downregulated the expression of MMP2 and MMP9, which are indicators of cell migration, and the phenotypic assays also suggested that the drug significantly inhibited the migration ability of both ovarian cancer cell lines." (PMID 37206208, 2023). "As both MMP-2 and EMMPRIN impact extracellular remodeling, this suggests that in vitro models for studying chemotherapy response in ovarian cancer may need to incorporate the stromal cells and extracellular matrix to better capture how tumor cells will respond." (PMID 36077825, 2022). "In addition, the application of CAP-treated solutions to ovarian cancer cells in vitro has been shown to decrease MMP9 but not MMP2 mRNA expression." (PMID 35216069, 2022). "Studies have shown that in ovarian cancer cells with high MMP-9 expression, the combined use of MMP9/MMP2 inhibitors and cisplatin could significantly enhance cytotoxicity, confirming that MMP9 is a potential therapeutic target for drug-resistant ovarian cancer." (PMID 33763485, 2021). "In summary, we believe that DLEU1 promotes the pathogenesis and development of epithelial ovarian cancer through its interaction with miR‐490‐3p, thereby altering the expression of the miR‐490‐3p target genes, that is, CDK1, CCND1 and SMARCD1, as well as the expression of MMP2, Bcl‐xLand P70S6K." (PMID 28598010, 2017).
ovarian carcinoma (continued). "As both CD44 and MMP2 are inducer of epithelial-mesenchymal-transition (EMT),which strengthens our confidence that WFCD2 might participate in tumor metastasis and disease processes by regulating the progression of EMT in ovarian cancer cells." (PMID 28679402, 2017). "However, other possible tumor metastatic promoting molecules (MMP‐2, MMP‐9) and repressors (E‐cadherin, β‐catenin) could also be involved in the regulation of ovarian cancer metastasis." (PMID 28401704, 2017). "Thus the independent prognostic value of MMP-2 and MMP-14 expression in ovarian cancer is limited." (PMID 27038607, 2016). "Furthermore the human ovarian cancer cells did not express MMP2, which was expressed in the mouse tumor cell lines." (PMID 27602775, 2016). "Additionally, AXL has been shown to regulate MMP-1, MMP-2 and MMP-9 expression in ovarian cancer." (PMID 27764792, 2016). "However, in ovarian cancer, MMP-2 rather than MMP-9 regulation by TGase 2 has been reported, indicating that different MMPs are regulated by TGase 2 in different types of cancer." (PMID 21943122, 2011). "In addition, MMPs such as MMP2 and MMP9 could be prognostic biomarkers for ovarian cancer." (PMID 33024414, 2020). "Low BCL9 expression also downregulated the expression of MMP2 and MMP9 in ES-2 cells, suggesting that BCL9 might dissolve the extracellular matrix of ovarian cancer cells by promoting the expression of MMP2 and MMP9, further promoting the invasion and metastasis of ovarian cancer cells." (PMID 31827404, 2019). "In addition, it was demonstrated that in SKOV-3 and OVCAR-3 ovarian cancer cells, the ablation of uPA expression results in a decrement of complete VM structures formation and such mechanism involves the participation of AKT/mTOR/MMP-2/Laminin5γ2 signal pathways." (PMID 31612116, 2019). "Tumor-derived MMP2 and MMP9 expression has been identified as a negative prognostic indicator in ovarian cancer patients, predicting lower overall survival rates." (PMID 40558552, 2025). "MMP-2, MMP-3, MMP-11 and MMP-26 have not shown potential as stand-alone biochemical markers in ovarian cancer diagnosis." (PMID 38892452, 2024). "MMP-2 and MMP-9 activity was detected in cervical, breast and ovarian carcinoma and ascites of patients with epithelial ovarian cancer (EOC) but not in the serum of these patients." (PMID 32581215, 2020). "Eight polymorphisms (MMP2 C-735T, MMP7 A-181G, MMP8 rs11225395, MMP9 rs6094237, MMP12 rs2276109, MMP20 rs2292730, MMP20 rs12278250, MMP20 rs9787933) were reported associated with ovarian cancer risk, while other polymorphisms could not be associated with ovarian cancer risk." (PMID 28957437, 2017). "In this study, we assessed the impact of melatonin on activity and expression levels of MMP-2 and MMP-9 in both stem and non-stem ovarian cancer cells." (PMID 29213108, 2017). "MMP-2 expression in ovarian cancer was higher as the clinical stage increased and MMP-2 positive expression was significantly higher (P < 0.05) in ovarian cancers with metastasis than without metastasis." (PMID 24245968, 2013). "A recent study showed that JNK, but neither ERK1/2 nor p38 MAPK, was critical for GnRH-mediated production of MMP-2 and MMP-9 in human ovarian cancer cells." (PMID 20074375, 2010).